MYBPH (myosin binding protein H)
Description:
Binds to myosin; probably involved in interaction with thick myofilaments in the A-band.
Tractability: PROTAC: ubiquitination databases record sites on it.
Gene: Protein-coding gene on chromosome 1 (203,167,811 to 203,175,880, reverse strand). Ensembl gene ENSG00000133055.
Subcellular location (Human Protein Atlas): Mitochondria; Nucleoli; Nucleoplasm
Gene Ontology:
Molecular function: protein binding; structural constituent of muscle
Biological process: regulation of striated muscle contraction; sarcomere organization
Cellular component: M band
Genetic constraint (gnomAD): Loss-of-function variants: 49 observed, 52.34 expected, observed/expected ratio (o/e) 0.94, 90% interval 0.74 to 1.19. The upper end of that interval is the gene's LOEUF score, 1.19, which puts it in group 5 of 6, group 1 being the genes least tolerant of losing a copy. Missense variants: 558 observed, 617.16 expected, observed/expected ratio (o/e) 0.9, 90% interval 0.84 to 0.97. Synonymous variants: 239 observed, 245.66 expected, observed/expected ratio (o/e) 0.97, 90% interval 0.88 to 1.08.
Homologues: Orthologues: chimpanzee MYBPH (98% identical), macaque MYBPH (96% identical), guinea pig MYBPH (87% identical), mouse Mybph (86% identical), pig MYBPH (85% identical), rabbit MYBPH (83% identical), rat Mybph (81% identical), dog MYBPH (69% identical), tropical clawed frog mybph (54% identical), zebrafish mybpha (50% identical), zebrafish mybphb (48% identical), Caenorhabditis elegans C34F6.10 (17% identical), and 1 more. Paralogues in human: MYBPHL (50% identical), MYBPC2 (49% identical), MYBPC1 (48% identical), MYBPC3 (47% identical), IGSF22 (27% identical), MYOM2 (24% identical), MYOM3 (23% identical), MYOM1 (23% identical), OBSL1 (17% identical), FNDC3A (17% identical), FNDC3B (16% identical).
Diseases named in the same sentence as MYBPH in open-access papers:
MYBPH is named in the same sentence as 22 diseases in open-access papers, as found by Europe PMC text mining. Sharing a sentence is not in itself a finding about the gene and the disease. The quoted sentences say what the papers report.
glioma (5 papers, 2022 to 2024). A benign or malignant brain and spinal cord tumor that arises from glial cells (astrocytes, oligodendrocytes, ependymal cells). "Nevertheless, HOXA5, PTPN2, WT1, HOXD10, POSTN, ADAMDEC1 and MYBPH were overexpressed in ATRX-mt glioma tissues with high-risk scores compared with low-risk scores." (PMID 37812190, 2023). "In the test cohort, HOXA5, PTPN2, WT1, HOXD10, POSTN, ADAMDEC1 and MYBPH levels were elevated in glioma tissues with high-risk scores." (PMID 37812190, 2023). "In the present study, we investigated the expression levels of MYBPH and also evaluated the association between MYBPH expression levels and prognosis of glioma." (PMID 35087137, 2022). "Similarly, in GBM, NDUFA6-DT demonstrates a negative correlation with SUMF1, CD109, MUC11, and MYBPH, which are all implicated in promoting glioma progression." (PMID 38674418, 2024). "MYBPH expression was positively associated with glioma grade (P = 0.002) and KPS score (P = 0.022)." (PMID 35087137, 2022). "Moreover, MYBPH expression was significantly associated with high tumor aggressiveness and poor outcomes in glioma patients." (PMID 35087137, 2022). "In glioma tissues from the high-risk group of the training cohort, HOXA5, PTPN2, WT1, HOXD10, POSTN, ADAMDEC1 and MYBPH were highly expressed." (PMID 37812190, 2023). "Overexpression of PCDH18, PPL, DEPP1, VASN, KCNE4, MYBPH, and C5AR2 in glioma and low expression of MARCH4 were associated with poor survival." (PMID 39281062, 2022). "To further illustrate the relationship between survival and MYBPH expression in glioma, we analysed two public databases, namely the GEPIA database and three CGGA datasets." (PMID 35087137, 2022). "Overexpression of PCDH18, PPL, DEPP1, VASN, KCNE4, MYBPH, and C5AR2 genes or low expression of MARCH4 gene in glioma patients was associated with poor survival." (PMID 39281062, 2022). "Through TCGA database, we identified that the eight key genes (PCDH18, PPL, DEPP1, VASN, KCNE4, MYBPH, C5AR2, and MARCH4) were associated with the survival of patients with glioma." (PMID 39281062, 2022). "We observed that MYBPH expression was higher in GBM tissues than in corresponding peritumor tissues and normal tissues and its expression was significantly associated with glioma grade (P = 0.002) and a lower Karnofsky Performance Scale score (P = 0.022)." (PMID 35087137, 2022). "The group with higher MYBPH expression had a poor prognosis of primary glioma in Dataset 1 (ID: mRNAseq_325) (P < 0.0001)." (PMID 35087137, 2022). "In conclusion, our findings indicate that MYBPH is positively correlated with the prognosis and grade of glioma." (PMID 35087137, 2022). "These experimental results showed that MYBPH contributes to the progression of glioma by promoting cell migration." (PMID 35087137, 2022). "Downregulation of MYBPH attenuated the migration capacity of glioma cells in the wound healing and transwell assays." (PMID 35087137, 2022). "In conclusion, our study revealed that an immune signature based on HOXA5, PTPN2, WT1, HOXD10, POSTN, ADAMDEC1 and MYBPH expression effectively predicted the prognosis of ATRX-wt glioma patients, and demonstrated that immunotherapy was effective for low-risk patients." (PMID 37812190, 2023). "A receiver operating characteristic curve analysis indicated that HOXA5, PTPN2, WT1, HOXD10, POSTN, ADAMDEC1 and MYBPH had significant prognostic value for the survival of ATRX-wt glioma patients (AUC = 0.84, 0.81, 0.79, 0.91, 0.80, 0.79 and 0.85, respectively)." (PMID 37812190, 2023). "The results showed that MYBPH was highly expressed in glioma tissues." (PMID 35087137, 2022). "To do this, we knocked down MYBPH in glioma cells using shRNA constructs." (PMID 35087137, 2022). "In conclusion, MYBPH might serve as a valuable prognostic marker and a potential therapeutic target for glioma." (PMID 35087137, 2022).
glioma (continued). "Therefore, MYBPH expression is expected to be positively correlated with glioma grade, hinting that it might have a functional role." (PMID 35087137, 2022). "Furthermore, we explored the role of MYBPH in the biological behavior of a glioma cell line." (PMID 35087137, 2022). "We constructed a risk model using HOXA5, PTPN2, WT1, HOXD10, POSTN, ADAMDEC1 and MYBPH expression data from a cohort of patients in TCGA, and found that it had significant prognostic value for ATRX-wt glioma patients." (PMID 37812190, 2023). "Of the 508 patients with glioma, the expression of PCDH18 (p < 0.001), DEPP1 (p < 0.001), VASN (p < 0.001), KCNE4 (p < 0.01), MYBPH (p < 0.001) and MARCH4 (p < 0.01) genes was significantly different between G2 and G3." (PMID 39281062, 2022). "Moreover, the deletion of MYBPH could inhibit the migration of glioma cells." (PMID 36193073, 2022). "Knockdown of MYBPH in glioma cells could not affect the cell viability, apoptosis and cell cycle." (PMID 35087137, 2022).
lung adenocarcinoma (4 papers, 2021 to 2024). A carcinoma that arises from the lung and is characterized by the presence of malignant glandular epithelial cells. "The ChIP-seq data indicate that NKX2-1 binds to five regions (far distal, distal and proximal upstream, and third and sixth introns) of the locus of MYBPH, a product of which is involved in cell motility and metastasis of lung adenocarcinoma." (PMID 33980985, 2021). "In the context of lung adenocarcinoma, MYBPH acts as a lineage-survival oncogene." (PMID 38172792, 2024). "MYBPH is a transcriptional target of TTF-1, a master regulator of lung development that plays a role as a lineage-survival oncogene in lung adenocarcinoma development." (PMID 37780567, 2023). "MYBPH has been reported to be a transcriptional target of TTF-1 and inhibits ROCK1 activity to reduce cell motility and metastasis in lung adenocarcinoma cells." (PMID 35087137, 2022).
glioblastoma (2 papers, 2022). The most malignant astrocytic tumor (WHO grade IV). "We showed that MYBPH is a novel biomarker that is variably expressed in glioblastoma (GBM)." (PMID 35087137, 2022).
lung carcinoma (2 papers, 2016 to 2023). "MYBPH is a transcriptional target of TTF-1, a master regulator of lung development that acts as a lineage-survival oncogene in the formation of lung cancer." (PMID 37664033, 2023). "Co-expression analysis revealed that ACSL1 was coexpressed with MYBPH, PTPRE, PFKFB3, SOCS3 in colon cancer and with LRRFIP1, TSC22D1 in lung cancer." (PMID 27171439, 2016).
bladder cancer (1 paper, 2021). "Importantly, MYH6 expression levels were significantly associated with age in bladder cancer, while MYBPH exhibited a negative correlation with age." (PMID 33436826, 2021).
dermatomyositis (1 paper, 2026). Dermatomyositis (DM) is a type of idiopathic inflammatory myopathy characterized by evocative skin lesions and symmetrical proximal muscle weakness. "Using LASSO regression, SVM, random forest (RF), GBM, GLM, KNN, and NNET machine learning algorithms, four core genes were identified: SAA1, NACAD, SLC14A1, and MYBPH, all of which were highly expressed in dermatomyositis lesion tissues." (PMID 41911226, 2026).
diabetes (1 paper, 2016). "Also, Ras associated with diabetes (RRAD) and Myosin binding protein H (MYBPH) that is involved early in skeletal muscle development was suppressed upon treatment suggesting reduced fiber regeneration." (PMID 27287443, 2016).
invasive breast carcinoma (1 paper, 2022). A carcinoma that infiltrates the breast parenchyma. "Recent studies have suggested that MYBPH can be used to predict the prognosis of invasive breast cancer and lung adenocarcinoma." (PMID 35087137, 2022).
ischemia (1 paper, 2024). A hypoperfusion of the BLOOD through an organ or tissue caused by a PATHOLOGIC CONSTRICTION or obstruction of its BLOOD VESSELS, or an absence of BLOOD CIRCULATION. "Being a key player of contractile apparatus, MYBPH is actively involved in the compensatory mechanisms following ischemia." (PMID 39302489, 2024).
cancer (7 papers, 2014 to 2024). A tumor composed of atypical neoplastic, often pleomorphic cells that invade other tissues. "MYBPH was found to suppress Rho-associated coiled-coil containing protein kinase 1 and inhibit actin organization, thus impairing single cell motility, increasing collective cell migration, and reducing cancer invasion and metastasis." (PMID 37812190, 2023). "Among the identified FRGs, MYBPH, SOST, SPRR2A, and CRNN were notably upregulated in the high-risk group, implying their potential involvement as cancer-promoting genes in BLCA development." (PMID 38172792, 2024). "ADORA1 and the top 4 significant genes, including MYBPH, FAM178B, CHI3L1 and METTL7B were selected as the hub genes for genetic variation, interrelationship, cancer pathway and drug susceptibility analysis." (PMID 34093805, 2021). "Additionally, we observed significant expression of CLDN6, CES1, SOST, SPRR2A, MYBPH, CGB5, and KRT1 in the high-risk group, suggesting their potential involvement as cancer-promoting genes in BLCA development." (PMID 37780567, 2023). "Moreover, DSG1, C6orf15, SOST, SPRR2A, SERPINB7, MYBPH, and KRT1 were considerably expressed in the high-risk group, indicating their potential roles as cancer-promoting genes in the development of BLCA." (PMID 37664033, 2023). "MYBPH activation eventually results in inhibition of cancer invasion and metastasis." (PMID 31196060, 2019). "Another hypothesis proposes that NKX2.1 negatively regulates the expression of myosin binding protein H and increases the migratory ability of tumor cells, thereby functioning as a cancer-promoting gene." (PMID 25478793, 2014).
tumor (7 papers, 2011 to 2025). "The association of high MYBPH expression with poor prognosis in newly diagnosed GBM patients and increased expression in recurrent GBM is indicative of its role in tumor aggressiveness." (PMID 35087137, 2022). "In order to further investigate the influence of MYBPH knockdown on tumor growth in vivo, we constructed mice xenograft models via the subcutaneous injection of U87 cells transfected with either shMYBPH (shMYBPH#3) or shCtrl." (PMID 35087137, 2022). "Mechanistically, the results suggested that MYBPH might promote tumor progression by improving tumor invasion and migration." (PMID 35087137, 2022). "Several experimental studies on cells and animals have demonstrated that MYBPH might play an important role in tumor progression." (PMID 35087137, 2022). "Univariate independent prognostic analysis showed that age (p < 0.001), tumor grade (p < 0.001), PCDH18 (p < 0.05), PPL (p < 0.01), DEPP1 (p < 0.01), VASN (p < 0.001), KCNE4 (p < 0.001), MYBPH (p < 0.001), C5AR2 (p < 0.01), and MARCH4 (p < 0.01) gene expression levels were significantly different." (PMID 39281062, 2022). "In addition, we uncovered that the expression of MYBPH and IGFBP6 expression was appreciably connected to tumor prognosis." (PMID 36193073, 2022). "In addition, immunohistochemical results showed that MYBPH was upregulated in clinical specimens from GBM patients and MYBPH expression was higher in tumor tissues than in the corresponding peritumor tissues and normal tissues." (PMID 35087137, 2022).
MYBPH also shares sentences with these, for which no sentence is quoted: infection (7 papers); measles (2); viral infection (2); bladder tumor (1); brucellosis (1); cardiomyopathy (1); colon cancer (1); colorectal cancer (1); hypospadias (1); malaria (1); myopathy (1).